RNU6-167P (RNA, U6 small nuclear 167, pseudogene)
Gene: Small nuclear RNA gene on chromosome 18 (31,345,362 to 31,345,467, reverse strand). Ensembl gene ENSG00000207019.
Homologues: Orthologues: chimpanzee U6 (99% identical), macaque U6 (89% identical), guinea pig U6 (80% identical), dog U6 (66% identical), dog U6 (65% identical), mouse Gm25549 (58% identical). Paralogues in human: RNU6-33P (85% identical), RNU6-1 (84% identical), RNU6-2 (84% identical), RNU6-3P (84% identical), RNU6-42P (84% identical), RNU6-4P (84% identical), RNU6-5P (84% identical), RNU6-6P (84% identical), RNU6-891P (84% identical), RNU6-9 (84% identical), RNU6-10P (83% identical), RNU6-12P (83% identical), and 1288 more.